FN1 (fibronectin 1)
Diseases named in the same sentence as FN1 in open-access papers (continued):
Sharing a sentence is not in itself a finding about the gene and the disease.
schizophrenia (4 papers, 2014 to 2022). A major psychotic disorder characterized by abnormalities in the perception or expression of reality. "In contrast, FN1 mRNA, which is highly expressed in peripheral macrophages relative to microglia, was increased in the high inflammatory schizophrenia subgroup." (PMID 33133060, 2020). "By inflammatory subgroup, FN1 mRNA (F = 4.58, df = 51,2, p = 0.015) was increased in the midbrain in schizophrenia cases with a high inflammatory biotype." (PMID 33133060, 2020). "FN1 mRNA was increased in the high inflammatory/schizophrenia subgroup compared to the control group (63.6%, p = 0.004); however, the low inflammatory/schizophrenia subgroup had intermediate FN1 expression." (PMID 33133060, 2020). "We found CD163+ cells around blood vessels and in the parenchyma and increases in ICAM1, CD163, CD64, and FN1 mRNAs as well as increases in all complement transcripts in the midbrain of schizophrenia cases with high inflammation." (PMID 33133060, 2020). "In schizophrenia-coagulation network, the SCZCGs including F8, FN1 and FGL1 are differential expressed candidate genes which are associated with coagulation function." (PMID 25522158, 2014). "Here, we hypothesized that markers consistent with infiltrating macrophages (ICAM1, CD163, and FN1 mRNAs) would be increased in midbrain parenchyma near dopamine cell bodies in people with schizophrenia and a high inflammatory biotype." (PMID 33133060, 2020). "Thus, disrupted interactions between ARC and ECM molecules, especially FN1, may contribute to the pathophysiology of schizophrenia." (PMID 35562887, 2022). "By diagnosis, gene expression of FN1, expressed by peripheral macrophages and not microglia, was increased in the midbrain in schizophrenia compared to controls (F = 5.88, df = 52,1, p = 0.019, covaried with RIN)." (PMID 33133060, 2020).
small cell lung carcinoma (4 papers, 2014 to 2023). Small cell lung cancer (SCLC) is a highly aggressive malignant neoplasm, accounting for 10-15% of lung cancer cases, characterized byrapid growth, and early metastasis. "Downstream target proteins including LAMC1, LAMC3, CDK2 and FN1 were enriched in the cancer‐related pathways in small cell lung cancer." (PMID 35668574, 2023). "Small cell lung cancer (SCLC) has ECM enriched in FN1 as well as collagen IV and tenascin that reduce the apoptosis induced by multiple drugs, including doxorubicin, cyclophosphamide and etoposide." (PMID 33731188, 2021). "Additionally, ITGA2 and FN1 were associated with GO terms and pathways related to extracellular matrix (ECM) organization and cancer (hsa05222: small cell lung cancer, hsa04512: ECM-receptor interaction, hsa05200: pathways in cancer)." (PMID 30414611, 2018).
synovial chondromatosis (4 papers, 2020 to 2025). Synovial chondromatosis is a type of non-cancerous tumor that arises in the lining of a joint. "Similarly, FN1, which encodes a glycoprotein present on the cell surface or in the extracellular matrix associated with synovial osteochondromatosis and synovitis, was upregulated in different synovial cell types during aging." (PMID 38092362, 2024). "Additionally, fluorescence in situ hybridization did not detect any gene rearrangement of fibronectin 1 (FN1), which is frequently observed in synovial chondromatosis and CHS arising from it." (PMID 39379548, 2025).
tuberculosis (4 papers, 2012 to 2025). A chronic, recurrent infection caused by the bacterium Mycobacterium tuberculosis. "Given the significance of fibronectin 1 (FN1) and collagen in the progression of extracellular matrix (ECM) remodeling within tuberculosis granulomas, our study aimed to assess their expression levels during Mtb infection." (PMID 39431015, 2024).
Type 1 diabetes (4 papers, 2014 to 2025). "Moreover, the KEGG enrichment analysis was used to identify the critical pathways for C3 FN1+ TCs, including ribosome, allograft rejection, and type I diabetes mellitus." (PMID 40612060, 2025). "Type 1 diabetes induced a significant upregulation in the mean fold change of relative mRNA expression of the renal cytoskeleton (stress indicators): desmin, vimentin, nestin, fibronectin-1, Coli-1, and α-SMA." (PMID 38044936, 2023). "Similarly, FN1 transcript levels were reduced during type 1 diabetes and further lowered in scWAT and rWAT and only slightly increased in eWAT by insulin." (PMID 25170835, 2014).
alveolitis (3 papers, 2014 to 2025). "Importantly, blocking the C5a/C5aR1 signaling either before or after the initiation of fibrosis led to significant reductions in lung tissue cell numbers, alveolitis scores, Ashcroft scores, collagen deposition, and the expression of fibrosis-related genes, including Acta2, Col1a1, Col3, and Fn1." (PMID 40867551, 2025).
amyotrophic lateral sclerosis (3 papers, 2020 to 2024). Amyotrophic lateral sclerosis (ALS) is a neurodegenerative disease characterized by progressive muscular paralysis reflecting degeneration of motor neurons in the primary motor cortex, corticospinal tracts, brainstem and spinal cord. "For instance, FN1 and SIK3 are associated with spondyloepiphyseal dysplasia, PADI2 is related to sclerosis, ERBB4 is connected to amyotrophic lateral sclerosis (ALS), and B3GNT2 and BACE1 are associated with muscular dystrophy and muscular inflammation, respectively." (PMID 38788487, 2024). "In addition, FN1 can influence the development of amyotrophic lateral sclerosis, one of the neurodegenerative diseases, by affecting the NF-κB pathway." (PMID 36118693, 2022).
atrial fibrillation (3 papers, 2020 to 2022). A disorder characterized by an electrocardiographic finding of a supraventricular arrhythmia characterized by the replacement of consistent P waves by rapid oscillations or fibrillatory waves that vary in size, shape and timing and are accompanied by an irregular ventricular response. "Of the genes identified in the present network analysis, only FN1 has been associated with atrial fibrillation." (PMID 32118046, 2020).
benign prostatic hyperplasia (3 papers, 2019 to 2025). A non-cancerous nodular enlargement of the prostate gland. "FN1 is a core component of the tumor matrisome and was upregulated in metastatic PC patients compared with normal and benign prostatic hyperplasia samples." (PMID 36749798, 2023).
chronic obstructive pulmonary disease (3 papers, 2020 to 2022). A chronic and progressive lung disorder characterized by the loss of elasticity of the bronchial tree and the air sacs, destruction of the air sacs wall, thickening of the bronchial wall, and mucous accumulation in the bronchial tree. "Moreover, FN1 was found to be up-regulated in the blood-derived EVs of smokers and patients with chronic obstructive pulmonary disease by proteomic methods." (PMID 32916986, 2020).
cognitive decline (3 papers, 2021 to 2024). "Brain expression of FN1 in cognitively unaffected homozygous APOEε4 carriers is lower than in those with AD, suggesting that FN1 may be involved in AD-related pathology and cognitive decline." (PMID 38699298, 2024). "Brain expression of cognitively unaffected homozygous APOEε4 carriers had significantly lower FN1 deposition and less reactive gliosis compared to homozygous APOEε4 carriers with AD, suggesting that FN1 might be a downstream driver of APOEε4-mediated AD-related pathology and cognitive decline." (PMID 38598053, 2024).
colon adenocarcinoma (3 papers, 2020 to 2024). "In a colon adenocarcinoma study, ATP6V1C2 knock-down (KD) affected WNT pathway-related genes and epithelial-to-mesenchymal transition (EMT)-related genes, with a decrease in fibronectin-1, vimentin and increase in E-Cadherin, thus attenuating metastasis." (PMID 39696035, 2024).
diabetic cardiomyopathy (3 papers, 2014 to 2022). Diabetic cardiomyopathy is a disorder of the heart muscle in people with diabetes. "We and others have previously shown the presence of focal fibrosis in diabetic cardiomyopathy and that there is increased expression of TGF-β1 signalling accompanied by enhanced COL4A1 and FN1 production." (PMID 24428157, 2014).
diabetic retinopathy (3 papers, 2011 to 2021). "The conducted immunohistochemical analysis confirmed an enhanced FN1 and COL1 protein expression in RNV, which are important ECM components associated with the thickening of the capillary vascular basement membrane in diabetic retinopathy." (PMID 34795670, 2021).
disc degeneration (3 papers, 2016 to 2022). "FN1 is a glycoprotein present at the cell surface and in the extracellular matrix that increases with disc degeneration." (PMID 35409356, 2022).
epilepsy (3 papers, 2016 to 2024). A brain disorder characterized by episodes of abnormally increased neuronal discharge resulting in transient episodes of sensory or motor neurological dysfunction, or psychic dysfunction. "As a result, we can predict that FN1 may be a candidate molecular marker associated with the occurrence and progression of epilepsy patients by affecting the astrocytes." (PMID 26742644, 2016). "The dysregulation of C1QB, C1S, CFI, SCN3B and FN1 may be used potential gene targets for epilepsy treatment." (PMID 26742644, 2016). "Additionally, C1QB, C1S, CFI, SCN3B and FN1 may be potential therapeutic targets for epilepsy." (PMID 26742644, 2016).
Ewing sarcoma (3 papers, 2022 to 2025). A small round cell tumor that lacks morphologic, immunohistochemical, and electron microscopic evidence of neuroectodermal differentiation. "Specifically, we identified that the expression of c-Jun and c-Fos in Ewing sarcoma cells is sufficient to upregulate the expression of multiple proteins, including fibronectin 1 (FN1), vinculin, vimentin, and fibroblast associated protein (FAP), that are downregulated by the EWS-FLI1 oncoprotein." (PMID 39201282, 2024).
Fibroadenoma (3 papers, 2016 to 2023). A benign tumor of the breast characterized by the presence of stromal and epithelial elements. "FN1 is a fibroadenoma protein involved in cell adhesion and migration." (PMID 36418670, 2023). "Using machine learning to build predictive regression models, we selected a five-gene transcript set (ABCA8, APOD, CCL19, FN1, and PRAME) to discriminate between fibroadenomas and phyllodes tumors." (PMID 26961242, 2016).
fibronectin glomerulopathy (3 papers, 2017 to 2025). A hereditary kidney disease characterized by proteinuria, type IV renal tubular acidosis, microscopic hematuria and hypertension that may lead to end-stage renal failure in the second to sixth decade of life. "Fibronectin glomerulopathy (FG) is caused by fibronectin 1 (FN1) gene mutations." (PMID 39859354, 2025). "We present a patient who developed fibronectin glomerulopathy, with no apparent familial history and no FN1 mutation, during the clinical course of rare congenital malformations, including persistent cloaca and congenital esophageal atresia." (PMID 28877681, 2017). "Thus she was diagnosed with fibronectin glomerulopathy, despite a negative family history of kidney disease and lack of any known missense mutations of fibronectin 1 gene." (PMID 28877681, 2017).
Granuloma (3 papers, 2014 to 2025). A compact, organized collection of mature mononuclear phagocytes, which may be but is not necessarily accompanied by accessory features such as necrosis. "Endothelial cells surrounding Mtb granulomas had a higher probability of sending out FN1 signals, which may indicate increased cellular senescence." (PMID 41586350, 2025). "Finally, Mtb granulomas have more FN1 senescent signaling from endothelial cells but lack MIF and SPP1 signaling for survival compared to MAH granulomas." (PMID 41586350, 2025).
hepatic diseases (3 papers, 2021 to 2025). "Aberrant splicing of FN1 may be related to hepatotoxic effects, as downregulated or dysfunctional SRSF3, and subsequent aberrant splicing of its targets including elevated EDA-Fn1, has been associated with liver disease." (PMID 37267159, 2023).
Hirschsprung disease (3 papers, 2019 to 2023). Hirschsprung disease (HSCR) is a congenital intestinal motility disorder that is characterized by signs of intestinal obstruction due to the presence of an aganglionic segment of variable extent in the terminal part of the colon. "It has also been demonstrated that, when upregulated, miR-206 targets and leads to the irregular expression of the FN1 gene in Hirschsprung disease patients." (PMID 37374977, 2023).
mesothelioma (3 papers, 2016 to 2023). A usually malignant and aggressive neoplasm of the mesothelium which is often associated with exposure to asbestos. "We found that the structural changes in M2 included ARG1, CD206, CD163, FN1, and MRP8, confirming the potential value of these markers to identify M2-like TAMs in patients with mesothelioma." (PMID 37958292, 2023).
nephritis (3 papers, 2017 to 2020). Inflammation of renal tissue. "Tgfb1, Acta2, Fn1 and Itgav mRNA expression in the glomeruli was increased in control mice with nephritis, and this increase was reduced in Pdgfra-CTGF cKO mice with nephritis." (PMID 28191821, 2017). "Glomerular gene expression of Tgfb1, α-smooth muscle actin (Acta2), fibronectin (Fn1) and integrin αv (Itgav) was increased in control mice with nephritis and this increase was reduced in Rosa-CTGF cKO mice with nephritis." (PMID 28191821, 2017). "In control mice with nephritis, Ctgf, Tgfb1, Acta2, Fn1, and Itgav mRNA expressions in the glomeruli were increased compared with control mice without nephritis." (PMID 28191821, 2017). "In addition to the increases in the expression levels of fibrotic makers such as Tgfβ1, Acta2, and Fn1, the glomerular mRNA expression of MCP-1 (Ccl2) and F4/80 (Adgre1) is increased in the control mice with anti-GBM nephritis, and this increase is reduced in the Rosa-CTGF cKO mice with nephritis." (PMID 30123390, 2018). "Expression of Fn1, Acta2, Tgfb1, Adgre1 or Ccl2 was tended to be reduced in Rosa-CTGF cKO mice with nephritis, but not significant." (PMID 28191821, 2017).
osteoporosis (3 papers, 2024 to 2025). A condition of reduced bone mass, with decreased cortical thickness and a decrease in the number and size of the trabeculae of cancellous bone (but normal chemical composition), resulting in increased fracture incidence. "Among them, ACHE and FN1 are already targeted by approved drugs, hinting at their potential therapeutic role in treating osteoporosis." (PMID 39526243, 2024). "Among these proteins, FN1 emerged as the most significant hub protein, highlighting its critical role in the molecular mechanisms driving osteoporosis." (PMID 39526243, 2024). "Importantly, the druggable evaluation revealed that ACHE and FN1 were targets of currently approved drugs, highlighting the importance of existing medications that could potentially be repurposed or serve as the basis for the development of new treatments for osteoporosis." (PMID 39526243, 2024). "Another study demonstrated that FN1 can effectively promote the differentiation as well as mineralization of osteoblasts by activating the WNT/β-catenin pathway, which can regulate bone-remodeling processes and play vital roles in the development of osteoporosis." (PMID 39526243, 2024).
ovarian tumors (3 papers, 2011 to 2025). "TNC, FN1 and COL1 expression in in ascites or ovarian tumor tissue are associated with an unfavorable prognosis and a lower survival (proteinatlas.org, accessed on 10/01/2023)." (PMID 38264656, 2023).
pancreatitis (3 papers, 2017 to 2022). Inflammation of the pancreas. "(D) qRT-PCR for transgenic Kras*, Fn1, Col1a1, Col3a1, Shh, Hbegf, Ereg, Areg, Tgfα and Egf in littermate control and iKras*;CD11b-DTR pancreata 3 weeks post pancreatitis and in iKras*;CD11b-DTR pancreata following DT treatment for 3 days and 1 week." (PMID 28980940, 2017). "Plasma levels of FN1 were significantly higher in PDAC patients (572.85 μg/mL): a 23-fold increase when compared to controls (25.03 μg/mL) and about 4-fold to 10-fold higher than compared to pancreatitis patients (59.2 μg/mL) and IPMN patients (135.94 μg/mL), respectively." (PMID 34944824, 2021).
rectal cancer (3 papers, 2015 to 2024). A primary or metastatic malignant neoplasm that affects the rectum. "Of note, using in vitro and in vivo models of rectal cancer, mutKRAS was recently shown to downregulate the expression of ECM components, such as Fn1, in fibroblasts." (PMID 36010567, 2022). "The biomarker signature was comprised of seven proteins (CADM1, LGALS3BP, HYOU1, FN1, VTN, LRG1, and MRC2) (Fig4A) that could predict the localization of rectal tumors especially well (86% of subjects with rectal cancer)." (PMID 26253080, 2015).
rectal tumors (3 papers, 2015 to 2022). "Protein network analysis highlighted the role of the LCN2–SLC22A17–MMP9 network in TME by the interaction with fibronectin 1 and claudin 7, especially in rectal tumors." (PMID 36211450, 2022). "Calcitriol significantly upregulated FN1 in normal colon, rectum, and rectal tumor organoids." (PMID 32824266, 2020).
serous ovarian cancer (3 papers, 2021 to 2025). "Previous studies have linked miR-101-3p to EMT inhibition, for instance, by targeting ZEB1 and affecting FN1 expression in serous ovarian cancer." (PMID 41382114, 2025).
thyroid nodule (3 papers, 2016 to 2021). A small circumscribed mass in the THYROID GLAND that can be of neoplastic growth or non-neoplastic abnormality. "In the present study, we developed a panel that presents excellent performance in discriminating benign from malignant thyroid nodules by combining only four genes (FN1, GABRB2, NGEF and HMGA2)." (PMID 27793213, 2016). "Several studies have shown that a lower elasticity of the thyroid nodule is correlated with a higher incidence of malignancy, although this could also be due to other histological features, such as the presence of fibrosis and the expression of galectin- 3 and fibronectin-1." (PMID 34129178, 2021).
uremia (3 papers, 2016 to 2022). A clinical syndrome associated with the retention of renal waste products or uremic toxins in the blood. "Meanwhile, by verifying the expression of these hub genes in the uremia-induced VC group, we found that Sost, Ibsp, Fn1, and Spp1 were highly expressed in calcified samples, while Col1a1 was lowly expressed." (PMID 35313524, 2022). "We constructed ROC curves of each hub gene separately and found that their area under ROC curves of Sost, Ibsp, Fn1, Col1a1, and Spp1 were all close to one in the uremia-induced VC group in GSE146638, with the normal group as control." (PMID 35313524, 2022). "Moreover, induction of uremia increased expression of fibrosis-related genes, most importantly Col1a1, Col3a1, and Fn1." (PMID 27992511, 2016).
amyloid diseases (2 papers, 2022 to 2024). "SRA proteins transthyretin, complement C3, albumin, fibrinogen, α-2-macroglobulin, fibronectin 1, and α-1-antitrypsin have been related to amyloidosis." (PMID 37902886, 2024).
autism (2 papers, 2017 to 2022). Persistent deficits in social interaction and communication and interaction as well as a markedly restricted repertoire of activity and interest as well as repetitive patterns of behavior. "Initially, the serum protein profile of children with autism revealed different expression of apolipoprotein B 100 (ApoB100), complement factor H related protein 1 (FHR1), fibronectin 1 (FN1), and C1q." (PMID 35204837, 2022).